PDPN (podoplanin)
Diseases named in the same sentence as PDPN in open-access papers (continued):
Sharing a sentence is not in itself a finding about the gene and the disease.
tumor (continued). "In the cases of human IBC, similar membrane podoplanin, membrane LYVE1, and nuclear Prox1 immunoreactivities were observed surrounding the tumor emboli." (PMID 39669476, 2024). "To investigate the identity of the increased VLSs in MOC2CX3CL1 tumors, we immunostained the tumor tissue using the blood vessel marker, CD34, and the LV marker, podoplanin (PDPN)." (PMID 38775151, 2024). "For example, macrophages expressing LYVE-1 and other LEC-related markers, such as podoplanin (PDPN), have been shown to localize to lymphatic regions and contribute to lymphangiogenesis in various tumor models." (PMID 38717149, 2024). "Dual immunofluorescence showed that PDGFR-β was expressed in both tumor cells (CK19+) and LECs (labeled by PDPN, LYVE-1 or PROX-1)." (PMID 37307823, 2024). "The interaction between podoplanin and the C-type lectin receptor (CLEC)-2 on platelets is believed to encourage tumor invasion and metastasis." (PMID 39061998, 2024). "Of note, we observed that CYTOR‐related nodal genes were mainly involved in EMT, p‐EMT or tumor invasion in HNSCC, including LAMB3, PDPN and FNDC3B." (PMID 38032139, 2024). "FAP, CD29, αSMA, PDPN and CD90 were all upregulated in tumour fibroblasts, while FSP1 was more highly expressed in NCL fibroblasts." (PMID 38582812, 2024). "The binding of PDPN to CLEC-2 depends on the glycosylation of residues at the O-glycosylation site of PDPN, which plays a crucial role in platelet aggregation and tumor metastasis." (PMID 38504248, 2024). "Tumour cores were stained with PanCK to identify tumour regions and the fibroblast markers FAP, PDPN, αSMA, FSP1 and CD90 were used to identify the key CAF subsets predominant in tumour tissue: CAF-S1, CAF-S4 and CAF-S5." (PMID 38582812, 2024). "In double-label immunocytochemical experiments with podoplanin (D2–40) which distinguished lymphatics from blood vessels (CD31), the vast majority (>90%) of vascular structures containing tumor emboli were lymphatics." (PMID 39669476, 2024). "Antibodies specific to podoplanin markers for lymphatic vasculature and CD31 for blood endothelial cells were used for tumor vasculature characterization." (PMID 39199565, 2024). "In order to understand, both FAP polyps and tumor samples were stained with VCAN (inflammatory marker), PDPN (CAF marker) and COL6A2 (normal fibroblast/basal lamina marker) and imaged." (PMID 39605357, 2024). "Suppression of metastatic tumours was observed in the lungs of WT mice injected with PDPN- cells, CLEC-2 KO mice injected with PDPN + cells and WT mice injected with PDPN- cells by H&E staining." (PMID 38561690, 2024). "PDPN expression in poorly differentiated carcinomas of SCC has been observed, indicating its role in tumor invasion and lymph node metastasis." (PMID 39403603, 2024). "On the other hand, in tumor matched 0923CAF after coculture with LK0923, the most evident changes were a significant decrease in both ACTA2 and POSTN and a strong increase of PDPN mRNA expression." (PMID 38822309, 2024). "They verified the roles of tumour growth promoter CAFs and podoplanin positivity in promoting cancer cell proliferation and evaluated the MIB-1 index by comparing podoplanin (+) and podoplanin (−) cancer cells in both groups." (PMID 38026900, 2023). "Podoplanin was expressed on stroma that encased tumor whilst DKK3 expression was present both within tumor and tumor-proximal stroma." (PMID 37350578, 2023). "We compared the transcriptome data between normal samples and GBM tumor samples, which indicated that ANXA1, PDPN, COL6A1, BCL3, RUNX1, and WWTR1 were upregulated and compared to normal samples, BCL11A was downregulated in GBM tumor samples." (PMID 37434432, 2023).
tumor (continued). "In conclusion, our study showed for the first time that a distinct cancer-promoting CAF subset, PDPN+ CAFs, secrete exosomal lncRNA FTX in the tumor microenvironment." (PMID 37993428, 2023). "Shown as within patient mean normalized count vs region type for DEG identified in A. (D) Representative immunohistochemical staining of podoplanin, DKK3 and C3 proteins in relation to tumor cells (T) in PDAC tissue." (PMID 37350578, 2023). "In this study, we developed a humanized and defucosylated mAb against PDPN (humLpMab-23-f) and evaluated its antibody-dependent cellular cytotoxicity (ADCC) and antitumor effect in xenograft models of human tumor cells." (PMID 37894446, 2023). "Following OvCa cell injection, mesothelial cells that coexpressed PDPN and GFP were observed on the surface of the tumor, as well as intratumorally." (PMID 36795484, 2023). "Apart from these EMT markers, podoplanin (PDPN), a glycosylated transmembrane protein, also serves as a critical functional effector during EMT process by promoting tumor metastasis." (PMID 37898647, 2023). "In this study, we produced a humanized and defucosylated anti-PDPN mAb (humLpMab-23-f) and evaluated its ability to induce ADCC and CDC or antitumor efficacy against PDPN-positive tumor cells." (PMID 37894446, 2023). "Recently, podoplanin (PDPN) and transforming growth factor-β (TGF-β), which stimulate interaction between tumor cells and fibroblasts, have been used as CAF markers." (PMID 37594996, 2023). "Therefore, targeting PDPN-positive CAFs using anti-PDPN mAbs could be a strategy for tumor therapy." (PMID 37894446, 2023). "We obtained five cell subpopulations, including four clusters (C0, C1, C2, C4) of tumor endothelial cells (PLVAP, VWA1, HSPG2, and INSR) and lymphatic endothelial cells (C3) (PDPN, CCL21)." (PMID 37715019, 2023). "To confirm the in vitro experimental observations, we established an OSCC tumor implantation model that involves the subcutaneous injection of SCC15 cells mixed with CAFs/PDPN-OE cells and CAFs/PDPN-Mock cells." (PMID 37993428, 2023). "Podoplanin (PDPN) is a transmembrane glycoprotein that plays a crucial role in several physiological and pathological processes, including tumor progression and metastasis." (PMID 38089632, 2023). "As expected, we found that the value of 3 PDEARGs (ANXA1, COL6A1, and PDPN) and key DETF (WWTR1) were co‐expressed significantly higher in the tumor core than in the peripheral of GBM tissue, specifically in the neoplastic cells." (PMID 37434432, 2023). "The interaction between the PDPN-CLEC-2 increases the angiogenesis and progression of tumor and metastasis." (PMID 36769180, 2023). "Immunohistochemical staining confirmed extreme polarization of podoplanin, DKK3 and C3 expression in relation to tumor proximity." (PMID 37350578, 2023). "In the tumor microenvironment (TME), PDPN expression is upregulated in the tumor stroma, including cancer-associated fibroblasts (CAFs) and immune cells." (PMID 35159384, 2022). "The combination of PDPN and CLEC-2 can induce platelet activation and thus promote tumor EMT by platelet-secreted TGFβ, while TGFβ neutralizing antibody can effectively inhibit PDPN-mediated distant metastasis." (PMID 35659308, 2022). "In this case, due to Ki-67/PDPN double staining, we found 15 tissue samples with LVI, counting the entire tumor tissue sample." (PMID 36077194, 2022). "CLEC-2 is a physiological binding receptor of podoplanin (PDPN), which is expressed on specific tumour cell types and involved in tumour cell-induced platelet aggregation and tumour metastasis." (PMID 35082906, 2022). "PDPN-targeted NIR-PIT using the anti-PDPN antibody, NZ-1, showed tumor suppression in both xenograft and orthotopic MPM models in immunodeficient mice." (PMID 35453596, 2022). "The effect of SAR131675 on tumor vascularization, (angiogenesis and lymphangiogenesis) was studied using CD34 (progenitor endothelial cell marker) and podoplanin (a LEC marker)." (PMID 35681695, 2022).
tumor (continued). "Based on the differential cell surface expression of PDPN and CD133, we isolated GSC subpopulations and evaluated their tumor-forming capacities." (PMID 36059614, 2022). "Using a previously validated flow cytometry strategy for CAF subtypes, we evaluated myCAFs (PDPN+Ly6C−MHCII−), iCAFs (PDPN+Ly6C+MHCII−), and apCAFs (PDPN+Ly6C−MHCII+) located within either hypoxic (Hypoxyprobe+) or normoxic (Hypoxyprobe−) tumor regions." (PMID 36109493, 2022). "By immunohistochemistry, the tumour cells were positive for pancytokeratin (focal), CD21, CD23, CD35, D2‐40 (podoplanin), and clusterin, and negative for CD3, CD20, CD30, CD45, ALK‐1, EMA, PAX5, PDL1, and S100 stains." (PMID 35846219, 2022). "PDPN expression is elevated in the majority of OSCC cells, and is a strong indicator of tumor aggression." (PMID 35177067, 2022). "Taken together, these data support that PDPN is interdependent with CLEC2, thus, the platelet CLEC2-PDPN axis is crucial for platelet-tumor cell interaction." (PMID 34987523, 2021). "To evaluate the extent of infiltration of CCA cells to LNs and LEC infiltration in CCA TME we stained tumor and liver LN section from orthotopic CCA mice with CK19/Podoplanin and CK19/LYVE1 respectively." (PMID 34831316, 2021). "For example, several tumor antigens that have been used for targeted therapies in human cancers are also identified in canine malignancies, including EGFR, HER2, VEGFR2, CD20, podoplanin, PD-1, and PD-L1." (PMID 34944112, 2021). "Analysing 128 murine tumours, we identified 5–6 main CAF populations and numerous minor ones based on the analysis of αSMA, FAPα, PDGFRα, PDGFRβ, CD26, and PDPN." (PMID 34016130, 2021). "Taken together, the PDPN-ERM axis can promote migratory capability and invasiveness of tumor cells, through either EMT process or cytoskeletal rearrangement." (PMID 34987523, 2021). "Endothelial cells from different sources were mixed and assigned to four cell types, including immune EDCs (CCL5 and CXCL13), lymphatic EDCs (PDPN and PROX1), tumor EDCs (ACKR1 and POSTN), and vascular EDCs (PLVAP and SLC9A3R2)." (PMID 34697289, 2021). "Flow cytometry-based quantification of tumor fibroblasts showed that artLCMV-TRP2 treatment precipitated a significant expansion of PDPN+ EYFP+ FSCs, while the proportion of EYFP+ PDPN+ FSCs in TDLNs remained unchanged." (PMID 34354077, 2021). "In sum, starting from the unbiased elucidation of the PDPN co-receptome, our work provides insights into PDPN functions and reveals the PDPN/CD177 axis as a possible modulator of fibroblast physiology in the tumor microenvironment." (PMID 34879110, 2021). "Podoplanin enhances the α-SMA expression, promotes the activation and proliferation of PSCs, and accelerates the migration and invasion of tumor cells." (PMID 34566887, 2021). "Podoplanin (PDPN) is a transmembrane receptor that participates in various physiological and pathological processes, such as cell motility, tumor metastasis and angiogenesis." (PMID 33123464, 2020). "The anti-PDPN therapy based on ADC and CAR-T strategies would improve the anti-tumor effects of P38Bf." (PMID 33238582, 2020). "POSTN expression in tumour stromal cells (i.e., CAFs) was evidenced on serial sections of tissues by the positive IHC reaction for α-smooth muscle actin (α-SMA), podoplanin (D2–40), and vimentin, which are characteristic markers of CAFs." (PMID 32987711, 2020). "Interestingly, given that function-blocking anti-PDPN antibodies have shown anti-tumor effects in mouse models of canine melanoma, our studies raise the possibility that these types of therapeutic strategies could potentially be developed for treating canine HSA." (PMID 32571313, 2020). "In human SCC and malignant pleural mesothelioma cell lines, PDPN induces EMT and promotes tumor cell invasion and distant metastasis by binding with platelets." (PMID 32380790, 2020).
tumor (continued). "The differential expression within the same tumor of canonical fibroblast cell markers such as FAP, podoplanin and αSMA clearly supports the simultaneous existence of phenotypically unique subpopulations." (PMID 33298926, 2020). "The localization pattern of anti-LAMA4 staining was similar to that of PDPN, with little staining being seen in normal splenic tissue and strong anti-LAMA4 staining being observed in the cytoplasm of HSA tumor cells encircling collagen fibrils." (PMID 32571313, 2020). "In SCC cells, podoplanin–ERM interaction is also critical for the stable localization of podoplanin at invadopodia, specialized cell-surface protrusions involved in tumor invasiveness." (PMID 33003440, 2020). "Podoplanin (PDPN), a small transmembrane mucin-like glycoprotein, is ectopically expressed on tumor cells." (PMID 33238582, 2020). "Differential expression analysis using GSEA and Limma of the 40 tumor transcriptomes consistently revealed DDR1, PDPN, and COL4A6 as top upregulated genes in tissues with ALI compared to those without (Table A1, Figure A1)." (PMID 32244515, 2020). "This highlights the role of platelets and podoplanin in promoting tumor progression via MMT, which is similar to the enhanced fibrin deposition, ECM formation and podoplanin expression observed in the induction and progression of EPS." (PMID 32532126, 2020). "Together with the localization of podoplanin at the invasive front of SCC tumors, podoplanin appears to play an important role in the detachment and invasion of tumor cells into the adjacent tumor stroma, which are crucial steps towards metastasis." (PMID 32599908, 2020). "Again, as with PDPN, anti-LAMA4 staining was also observed in the cytoplasm in the endothelial cells from tumor-adjacent blood vessels." (PMID 32571313, 2020). "Next, we performed IHC analysis of PDPN and LAMA4 on HSA tumor sections to confirm that these molecules are expressed in tumor tissue at the protein level and to investigate their localization." (PMID 32571313, 2020). "We next investigated the expression of mature PDPN and LAMA4 transcripts in tumor tissue and normal spleen using RT-PCR." (PMID 32571313, 2020). "With the aid of the YFP lineage tracer and the cell surface markers podoplanin and Sca-1, we isolated LSCC and LADC tumor cells, respectively, from CKFY mice by FACS." (PMID 30642944, 2019). "Immunohistochemistry (IHC) on serial sections from patient surgical samples showed the presence of POSTN, PDPN and MYH11 in spatially distinct areas of the tumour, suggesting expression of these markers by different CAF subpopulations." (PMID 30575030, 2019). "POSTN was present both at the invasive margin and in the centre of the tumours (juxta‐tumoural stroma [<100 μm] and pan‐stroma 23), as previously reported 24, while MYH11 and PDPN were found only in the centre (juxta‐tumoural stroma and pan‐stroma)." (PMID 30575030, 2019). "We observed that the PDPN and LAMB3 proteins were specifically expressed in OSCC cells at the tumor periphery." (PMID 31238980, 2019). "ROCK inhibition suppressed PDPN-induced tumor cell migration, highlighting the role of the RHOA/ROCK axis in CAF-dependent tumor invasion." (PMID 31106200, 2019). "miRNA-203 targets podoplanin (PDPN), a protein that promotes tumor cell-induced platelet aggregation, which enhances tumor metastasis." (PMID 30901831, 2019). "These podoplanin-positive fibroblasts, which express a genetic signature resembling FRCs, generated a dense ECM, preventing immune cells from going deeper in the tumor parenchyma, and inhibiting T-cell proliferation in a nitric oxide-dependent manner." (PMID 30736372, 2019). "In total, 699 tumor samples from 382 patients and 709 tumor samples from 388 patients were informative for CD34 and podoplanin staining, respectively." (PMID 31547460, 2019). "MS-1, an anti-PDPN antibody, which blocks PDPN/CLEC-2 interaction, significantly reduced tumour metastasis and tumour growth in vivo." (PMID 28737696, 2017).
tumor (continued). "Comparing with para-cancerous tissues, tumor tissues had significantly lower expression levels of LYVE–1 (P < 0.001) and VEGFR–3 (P = 0.013) and higher levels of Podoplanin (P = 0.016) and Prox–1 (P = 0.078)." (PMID 29162097, 2017). "In vitro and in vivo analyses revealed that podoplanin-mediated EMT resulted in increased invasiveness and extravasation of tumour cells." (PMID 28176852, 2017). "Established podoplanin mAbs indicate suppressive effect against platelet aggregation induced by podoplanin-expressed CHO and some podoplanin-positive tumor cells." (PMID 28674748, 2017). "Second, inflammation and tumor-mobilized BMDM often express lymphatic-specific markers such as VEGFR-3, LYVE-1, and podoplanin (PDPN)." (PMID 28598999, 2017). "The tumor cells are commonly positive for CD21, CD23, CD35, CXCL-13 and podoplanin (D2-40), the markers of normal follicular dendritic cells." (PMID 28438212, 2017). "Physiologically, podoplanin takes part in lymphatic vessel development and thrombus formation but in the presence of tumor cells may promote tumor growth and hematogenous tumor metastasis by inducing secretion of growth factors and inducing tumor emboli formation in the microvasculature." (PMID 28752248, 2017). "To identify NSCLC cell lines that induce lymphangiogenesis, we stained a panel of 13 NSCLC tumor xenograft samples from previous animal experiments with antibodies against LYVE-1 and podoplanin." (PMID 26950548, 2016). "We previously reported that podoplanin–CLEC-2 interaction was essential for podoplanin-induced platelet aggregation and tumor metastasis." (PMID 26684030, 2016). "Immunohistochemistry of paired tumour samples showed that regorafenib targets tumour stromal vasculature through down regulation of VEGFR-2 phosphorylation and podoplanin." (PMID 25889309, 2015). "The tumor formation rates of NCI-H82 cells co-injected with CAFs-Ctrl and of cells co-injected with CAFs-PDPN were 75% and 63%, respectively at 2 weeks and 88% and 100%, respectively, at 4 weeks (P = 0.59)." (PMID 25909164, 2015). "Increased expression of tumor promoters including TIMPs, c-myc, cyclin D1, TGF-α, EGFR, and PDPN are also often seen in these lesions." (PMID 25826087, 2015). "For instance, a tumor cell and a LEC compose two distinct environments with different signaling pathways and molecules active; upregulating PDPN in these distinct signaling milieus would likely have diverse outcomes." (PMID 22988448, 2012). "As a result, we confirmed that mouse podoplanin had a staining pattern similar to that of LYVE-1, indicating that the tumor cell nests were circumscribed with lymphatic endothelial cells." (PMID 21034514, 2010). "Celecoxib reduced levels of the lymphatic endothelial cell marker, podoplanin RNA by 87% in the MCF7/HER2-18 and 99.9% in the MDAMB231 tumours." (PMID 17285134, 2007). "Thus, podoplanin expression may be modulated by the environment of the tumour." (PMID 17179989, 2007). "The interaction between tumour cells and the ECM is a pre-requisite for cell migration and invasion and, indeed, podoplanin increased cell migration of MCF7 cells and HaCaT keratinocytes in the presence of E-cadherin expression." (PMID 17179989, 2007). "The assessment of lymphangiogenesis (podoplanin) and angiogenesis (CD31) was determined by quantitative PCR utilising snap-frozen tumour samples, which were stored in liquid nitrogen until use." (PMID 17285134, 2007). "Secretion of tissue factor and proinflammatory cytokines by tumor cells and the TME, overexpression of heparanase and podoplanin, impaired fibrynolysis and increased neutrophil extracellular trap formation lead to platelet hyperactivation resulting in hypercoagulability in PC." (PMID 41899496, 2026). "PDPN (podoplanin), a transmembrane glycoprotein broadly expressed by CAFs across tumor types, has been effectively targeted in preclinical models using monoclonal antibodies and CAR-T approaches, resulting in robust anti-tumor activity." (PMID 41198614, 2025).